SPI1 (Spi-1 proto-oncogene)
Diseases named in the same sentence as SPI1 in open-access papers (continued):
Sharing a sentence is not in itself a finding about the gene and the disease.
infection (continued). "SPI-1 and SPI-2 T3SS are expressed during the infection process at different stages." (PMID 29117268, 2017). "During mouse infections, Salmonella mutants lacking SsrB had high levels of hilA (SPI-1) transcriptional activity whereas introducing a constitutively active SsrB led to significant hilA repression." (PMID 28704543, 2017). "However, during early infection, a population of bacteria damages the SCV membrane by SPI-1 and escapes to the cytosol to obtain nutrients for rapid growth." (PMID 27412722, 2016). "We confirmed that infection with either wildtype S. typhimurium or S. typhimurium lacking the SPI-1 secretion system (which genetically limits S. typhimurium to activate NLRP3) induced inflammasome formation." (PMID 27011353, 2016). "This is in stark contrast to the autophagy of SPI-1-competent Salmonella in epithelia, which has previously been observed to occur early and transiently, with little co-localization between bacteria and LC3 evident beyond 2 hours post-infection." (PMID 24901456, 2014). "Except for MMP7, the gene expressions characterized in this study were not triggered after infection with the non-invasive SPI1 mutant of Salmonella Enteritidis." (PMID 23687968, 2013). "Whilst the infection with the wild-type Salmonella Enteritidis induced expression to a similar extent as in the time-dependent experiment, the SPI1 mutant essentially did not induce an immune response in the chicken cecum." (PMID 23687968, 2013). "Conversely, in this study we showed that the deletion of either SPI-1 or SPI-2 did not affect Salmonella virulence in a Galleria model of infection." (PMID 23951347, 2013). "This suggests that the absence of microbiota disruption during infections with SPI-1 or SPI-2 mutants in both our previous and current studies is not solely a consequence of reduced inflammatory influx but, rather, specific to neutrophil infiltration." (PMID 23155475, 2012). "Few studies have investigated the role of SPI1 and SPI2 during the infection of chickens." (PMID 19126220, 2009). "In chickens infected with the wild type strain and its isogenic mutant lacking the entire SPI1 (Δspi1), the Δspi1 cells were significantly reduced in the ceca at days three (P < 0.0001) and fourteen (P < 0.0001) post-infection." (PMID 19126220, 2009). "Salmonella pathogenicity island 1 (SPI-1) is not important for colonization of cecal contents in 1-day old Rhode Island Red chicks, at either 1,2, or 3 days post infection." (PMID 18922185, 2008). "Interestingly, on average, SPI-1 genes were poorly expressed during infection in cells lacking Gre factors, which is consistent with previous gene expression data from ΔgreA ΔgreB cells grown in broth culture." (PMID 38095872, 2024). "We propose a model where the SPI-1-dependent depletion of the PMF and the upregulation of adhesins upon HilD-activation enable flagellated Salmonella to rapidly modulate their motility during infection, thereby enabling efficient adhesion to host cells and delivery of effector proteins." (PMID 37315106, 2023). "The expression of IL9 and its transcription factor SPI1 in hydatid patients was significantly higher in focal tissue, suggesting the formation of chronic granuloma in hydatid by upregulating the expression of Th9 cells, IL9, and transcription factor SPI1 during infection." (PMID 37593762, 2023). "Because there were differences in intracellular bacterial burden between serovars, we compared the expression of SPI-1 and SPI-2 genes during infection as differences in virulence gene expression may contribute to differences in invasion and intracellular replication." (PMID 34669717, 2021). "SPI1 effectors are essential for gaining access to non-phagocytic target cells such as those in the gut epithelium, but this invasion step is bypassed in the intravenous infection route used for infecting zebrafish embryos." (PMID 31428591, 2019).
infection (continued). "To explore whether SsrB is involved in this inverse regulation during intracellular stages of infection, we analyzed the expression of invF (SPI-1) and ssaG (SPI-2) in WT bacteria and in bacteria lacking SsrB following macrophage infection." (PMID 28704543, 2017). "We then analysed whether ST infection resulted in pyroptotic cell death, as we have shown that infection of macrophages from the teleost fish gilthead seabream with WT ST, but not with its derivative isogenic SPI-1 mutant strain, triggers pyroptosis." (PMID 27363812, 2016). "In order to investigate the role of DksA in SPI1 and SPI2 expression, we constructed an S. Typhimurium ΔdksA strain and showed that an early stationary phase culture of the mutant strain was attenuated by 3.6-fold for invasion in a HeLa cell infection model when compared to the parent strain." (PMID 26039089, 2015). "In addition to SPI1 and SPI2, the alternative sigma factor, RpoS is known to be highly expressed during stationary phase in S. Typhimurium and has been shown to be required for the successful infection of mice." (PMID 26039089, 2015). "Therefore, shortly after infection, the SPI-1 T3SS of the S. Typhimurium Δasd mutant becomes non-functional and the bacteria mutant dies shortly after entering into mammalian cells." (PMID 24098123, 2013). "Furthermore, the transcription of T3SSs is generally induced by specific signals coming from their animal and plant hosts and therefore another open question is how the transcriptional induction of SPI-1 and SPI-2 operons occurs during infection of host plants." (PMID 21915285, 2011). "In addition, expression of Salmonella proteins including those of SPI-1 in vivo during the established phase of infection has not been extensively studied." (PMID 20529336, 2010). "SPI-1 genes were not identified as important for infection during recent Signature Tagged Mutagenesis screening in 2-week-old SPF Light Sussex chicks at 4 days post infection." (PMID 18922185, 2008). "We propose that upregulation of adhesive structures and depletion of the PMF after activation of SPI-1 injectisome expression might allow Salmonella to rapidly adjust their motility behaviour during host cell infection independent of flagellar gene expression and assembly." (PMID 37315106, 2023). "In this study, we hypothesized that the S. Typhi TolC would similarly play an essential role in bacterial adhesion and invasion during the infection of human cells and also investigated whether the lack of TolC will affect SPI-1 gene expression known to be upregulated during the bacterial invasion." (PMID 38029101, 2023). "Genetically wild-type but phenotypically nonexpressing individuals can both compete with SPI-1 mutants that might emerge during infection and maintain a population of individuals capable of SPI-1 expression that is necessary for systemic infection and transmission." (PMID 34154400, 2021). "To determine whether the colonization defects we observed were dependent on a functional T3SS-1 and host neutrophilic inflammatory response, we performed competitive infection experiments between the virulent WT and the ΔSTM3846 mutant both in the presence and absence of SPI-1." (PMID 26367458, 2015). "Notably, SPI-1 and -2 were vital in intestinal colonization of calves and pigs and to a lesser extent chickens, yet a Type I protein secretion system encoded by SPI-4 appeared to influence infection of calves, but not chickens or pigs." (PMID 23637626, 2013). "Independent of growth-phase prior to infection, the spe-mutant was significantly reduced, compared to the wt strain, in its ability to invade epithelial cells with invasion efficiency less than (exponential phase bacteria) or similar to (stationary phase) a SPI1 mutant (invH)." (PMID 22558361, 2012).
infection (continued). "In the second experiment, we infected the chickens with a mixture of the Δspi1 and the Δspi1 Δspi2 strains in order to verify whether the phenotype observed for the Δspi2 strain in the mixed infection with the wild type is reproducible when SPI1 is absent in the two competing strains." (PMID 19126220, 2009). "In our study, we highlight important differences in systemic and intestinal colonization levels between chick and murine serotype Typhimurium infections, and provide evidence that suggests that the role of SPI-1 may not be the same during colonization of both animal models." (PMID 18922185, 2008). "Unlike SopD, SopD2 is secreted into host cells by the SPI-2 T3SS but not the SPI-1 T3SS, and in epithelial cells, secretion is not detected until at least 5 h post-infection." (PMID 38673776, 2024). "To ensure SPI1-genes were not expressed, we grew S. Typhimurium in SPI2 inducing media prior to infection." (PMID 38055781, 2023). "However, a population of pYV-free cells might well be beneficial for Yersinia during infection, similar to Salmonella enterica and Pseudomonas aeruginosa, which have T3SS-positive and T3SS-negative subpopulations (although based on a different mechanism in Salmonella SPI-1)." (PMID 37228670, 2023). "However, at 3 h post infection, there were fewer ΔinvA mutant bacteria in the cytosol as compared to SPtA 9150 WT or ΔfepE, suggesting that vacuolar escape later during infection is dependent on the SPI‐1 T3SS but is not affected by the very long O‐antigen chains." (PMID 33355403, 2021). "Unlike SPI-1, the SPI-2 genes are induced in the systemic phase of infection, enabling bacteria to survive and replicate within macrophages." (PMID 33803635, 2021). "Our data showed that mutants deficient in LPS and flagella biosynthesis were attenuated in the chick embryo model, but SPI-1, SPI-2 and the PhoPQ regulon were not required for infection; further investigation is needed to confirm this finding." (PMID 31348776, 2019). "These genes were usually suppressed also after infection with the SPI2, phoP and aroA mutants but not with the SPI1 mutant." (PMID 26380970, 2015). "SPI1, aroA and phoP mutants were present at lower intracellular counts than the wild-type S. Enteritidis or the SPI2 mutant 4 h post infection but none of the comparisons reached statistical significance." (PMID 26380970, 2015). "In the murine salmonellosis model, SPI1 is needed for invading non-phagocytic cells in the small intestine, while SPI2 is crucial for the intracellular phase of infection." (PMID 33330118, 2020). "Relatively, the role of SPI-1 and SPI-2 in human infections is still not clearly defined." (PMID 31214517, 2019). "Furthermore, S. Seftenberg strains lacking SPI-1 have been isolated from human clinical cases, suggesting that for this serotype, the T3SS-1 is not required to establish infection in humans." (PMID 25653644, 2014). "The effectors secreted by the SPI-1 T3SS are responsible for bacterial entry into non-phagocytic cells and promote early biogenesis of the SCV, while effectors of the SPI-2 T3SS contribute to the evasion of cellular immune responses to infection, bacterial replication, and systemic spread." (PMID 38673776, 2024).
tumor (140 papers, 2008 to 2025). "Tumor spheroids infected with WT bacteria released higher amounts of LDH (53% of total maximum LDH release at 100%) compared to SPI-1-deficient (22%) or SPI-2-deficient (33%) strains." (PMID 39873483, 2025). "In the present study, we observed that CCL7, which can be upregulated by LINC01094-mediated SPI1, is linked to increased tumor M2 macrophage accumulation and malignant development of LUAD cells." (PMID 36118415, 2022). "The continuous overexpression of SPI1 in hematopoietic cells leads to the differentiation of macrophages, and SPI1 is an important regulatory factor for all states of tumour-associated macrophages (TAMs)." (PMID 35864510, 2022). "Of note, Ikzf1, Spi1, Tcf3, and Pax5 are normally expressed in induced B cell progenitors, which ensure tumor-free lymphopoiesis as reduction or loss of any of these master factors is associated with B cell leukemia." (PMID 34893754, 2022). "IL-9 mRNA levels in tumours showed a marked correlation with the Th9-associated transcription factors Irf4, Gata3, and Spi1, as well as with Socs3." (PMID 35793807, 2022). "The results indicated that expression of SPI1 was significantly up-regulated in the tumor, and was associated with a lower survival rate in GBM." (PMID 35361282, 2022). "SPI1 expression in tumor bulk tissues is associated with disease progression and poor prognosis, as well as high expression levels of immune markers and infiltration of immune cells." (PMID 36477668, 2022). "Another potential target for immunotherapy, oncogene SPI1, was also identified in tumor-associated macrophages at a single-cell level." (PMID 36430704, 2022). "Altogether, these results established a link between the FOLR2 gene and the expression of the PU.1-encoding SPI1 gene in tumor-associated macrophages." (PMID 32532019, 2020). "SPI1 is also a putative proto-oncogene associated with tumor progression, which encodes a protein that functions in the development of lymphocytes." (PMID 25514975, 2015). "The high recurrence of Spi-1 insertional mutation in Friend tumor cells suggested that Spi-1 overexpression was cooperative with the constitutive signaling from gp55/EpoR and sf-Stk/EpoR complexes to induce the malignant transformation of the proerythroblast." (PMID 18983647, 2008). "Moreover, survival analysis using the Kaplan-Meier plotter tool displayed that the upregulated expression of SPI1 in tumor mass was linked to short overall survival (OS) and disease-free survival (DFS) time in patients with GBM." (PMID 34434898, 2021). "Interestingly, we found that circSPI1 exerted an oncogenic function, distinct from its liner SPI1 gene encoding PU.1 that is known as a tumor suppressor." (PMID 33741901, 2021). "Overall, we confirmed that M2‐like macrophages induce the expression of SPI1 on tumor cells through IL8/IL10 to promote ITGβ8 transcription." (PMID 39535362, 2025). "These N2 neutrophils transfer the transcription factor spi-1 proto-oncogene (SPI1) to tumor cells via extracellular vesicles, thereby enhancing tumor glycolysis and lactate production, and accelerating tumor progression." (PMID 41152975, 2025). "In contrast, the M2‐like macrophage‐derived cytokines IL8 and IL10 promote the expression of ITGβ8 on tumor cells, and SPI1 mediates this effect." (PMID 39535362, 2025). "Flow cytometry (FCM) demonstrates that si-SPI1 concomitant with erastin further promotes lipid peroxidation levels in tumor cells." (PMID 41372608, 2025). "SPIC and MAFB were predominantly expressed in normal and adjacent tissues, while SPP1+ TAM-associated TFs (SREBF1, JUN, SPI1, and CREB1) showed peak expression in tumor core regions." (PMID 40725473, 2025). "After knocking down SPI1, the electron microscopy confirmed the increased density of tumor mitochondrial membranes and the reduction or disappearance of mitochondrial cristae." (PMID 41372608, 2025). "The transcription factor SPI1 plays a prominent role in tumor metabolism and is identified as a biomarker for NB." (PMID 40537738, 2025).
tumor (continued). "HE staining results showed that SPI1 overexpression enhanced cellular pleomorphism, nuclear/cytoplasmic ratios, mitotic figures, and surrounding stroma in tumor tissues, indicating elevated proliferative activity and malignancy." (PMID 40636695, 2025). "The elimination of hilD (the SPI-1 master regulator) resulted in a significant invasion defect with a mean reduction of 1.4 log CFU/well compared to WT, suggesting that SPI-1 played a significant role in early bacterial invasion of tumor cells." (PMID 39873483, 2025). "In order to find the mechanism of SPI1 transcriptional repression, we treated tumor cells with HDAC inhibitor (Entinostat) and PCR2 inhibitor for a Western blot assay." (PMID 41372608, 2025). "Both SPI-1 (ΔhilD)-deficient and SPI-2 (ΔssrB)-deficient strains were found to colonize (extracellular) and invade (intracellular) tumor cells to the same extent as WT at 1 DPI." (PMID 39873483, 2025). "From representative images of infected 3D tumor spheroids at 16 HPI, both SPI-1-deficient and SPI-2-deficient strains were observed at reduced levels compared to the WT consistent with the quantification of CFU." (PMID 39873483, 2025). "In a xenograft murine model, SPI1/CXCL12 was associated with increased tumor weights when SPI1 was present, while CXCL12 knockdown led to decreased tumor weights." (PMID 39409924, 2024). "This analysis revealed that network hubs – the likely mediators of network function and disease – were regulated by known oncogenic transcription factors in TNBC, including IRF8 and SPI1, both correlated with survival and tumor immunogenicity in TNBC." (PMID 37781176, 2023). "In summary, this research identified NMT1 as a tumor promoter in GC and revealed that SPI1 mediated NMT1 to facilitate GC cell viability, migration, and invasion by activating the PI3K/AKT/mTOR pathway." (PMID 36967718, 2023). "The most five active regulators were identical in tumor and normal tissues, SPI1, CEBPB, JUNB, FOS, and KLF4." (PMID 37335089, 2023). "Thirdly, in addition to OS tumor cells, the expressional levels of SPI1-TYROBP-FCER1G network in other potential cell types, such as myeloid cells and endothelial cells, in the microenvironment are still unclear." (PMID 35078433, 2022). "We then examined the expression of SPI1 in LA and found that SPI1 was significantly down-regulated in tumor samples (normal 59, cancer 535, p = 3 × 10−27)." (PMID 36101427, 2022). "Second, through CIBERSORT, Gene Ontology (GO) and the Kyoto Encyclopedia of Genes and Genomes (KEGG) analysis, we found that SPI1 is related to a variety of TICs and tumor-related signaling pathways." (PMID 35237521, 2022). "In OS, the under-expression of SPI1-TYROBP-FCER1G network in tumor cells or microenvironmental endothelial cells/myeloid cells can potentially attenuate the immune infiltration and T cell activation, leading to the metastasis/poorer prognosis of OS." (PMID 35078433, 2022). "Inhibition of the expression of SPI1 can effectively reduce the maturation and polarization of TAMs to play an anti-tumour role." (PMID 35864510, 2022). "We found circKPNB1 overexpression resulted in larger tumor volumes than the empty vector, while this promoting effect was reversed after SPI1 knockdown." (PMID 35945192, 2022). "The correlations between SPI1 expression and tumor-infiltrating immune cells (TICs) were analyzed using CIBERSORT and TIMER." (PMID 35237521, 2022). "In fact, Spi1 mRNA levels were significantly induced in tumor infiltrating T cells in WT mice as compared to lung T cells from mice lacking tumors." (PMID 35514957, 2022). "In summary, high expression level of SPI1 correlates with immune cells infiltration, resulting in an immunosuppressive microenvironment and exhaustion of tumor-specific T cells, leading to poor prognosis." (PMID 36477668, 2022). "To compare the mRNA expression levels of SPI1 in normal and tumor tissues among multiple human cancer types, we used the ONCOMINE and TIMER databases." (PMID 35237521, 2022).